CXCL12 (C-X-C motif chemokine ligand 12)
Diseases named in the same sentence as CXCL12 in open-access papers (continued):
Sharing a sentence is not in itself a finding about the gene and the disease.
lung carcinoma (continued). "The researchers found that individuals with the CXCL12 AA (high expressing genotype) and CXCR4 TT genotypes had higher odds ratios (an OR of 1.95, 95% CI 1.08–3.50, p = 0.018 and OR of 4.71, 95% CI 1.99–11.2, p < 0.0001, respectively) for lung cancer development." (PMID 30257500, 2018). "Further analysis of the anti-tumor effect of CXCL12 revealed that it was dependent on the presence of functional CD8+ T cells, in agreement with a previous study that demonstrated the importance of CD8+ T cells in CXCL12-mediated growth inhibition of melanoma and lung carcinoma." (PMID 20849618, 2010). "Quantitative gene expression patterns of CXCL12, CK7, CDH1, CTNNB1, HIF1A, MUC16, TGFBR2 and CD44v6 were analyzed from CTC, exosomes and cell free RNA of lung cancer patients with and without liver metastasis." (PMID 38877052, 2024). "In preclinical models of melanoma and lung cancer, elevated expression of insulin-like growth factor 1 (IGF-1) and the chemokine CXCL12/SDF-1 by non-irradiated CAFs have been shown to be responsible for radioprotective effects on cancer cells." (PMID 37170098, 2023). "In models of melanoma and lung cancer, elevated expression of insulin growth factor 1 (IGF-1) and chemokine CXCL12/SDF-1 by CAFs (non-irradiated) have been shown to be responsible for radioprotective effects on cancer cells." (PMID 34663337, 2021). "CXCL12, CK7, CDH1, CTNNB1, TGFBR2 and CD44v6 were upregulated in CTC as well as cfRNA whereas all these genes were downregulated in exosomes of primary lung cancer with and without metastasis." (PMID 38877052, 2024).
glioblastoma (126 papers, 2009 to 2026). The most malignant astrocytic tumor (WHO grade IV). "An analysis of public glioblastoma datasets has confirmed the association of CXCL12 with disease and PD-L1 expression." (PMID 38898023, 2024). "MiR-663 was also shown to decrease glioblastoma by targeting transcripts encoding CXCR4, the receptor of chemokine CXCL12 that is known to be involved in glioblastoma progression, and miR-663 overexpression prolonged survival of mice with glioblastoma." (PMID 29987196, 2018). "The results suggest that CXCL12/CXCR4 is involved in the progress of glioblastoma, regulating the expression of the molecules associated with stem-cell properties." (PMID 23961808, 2013). "In glioblastoma cells, the use of olaptesed pegol as a combination therapy has been reported to be effective in reducing the recruitment of tumor-associated macrophages due to CXCL12 increase after anti-VEGF therapy." (PMID 34976180, 2022). "When compared to using only anti‐EGFRvIII CAR‐NK cells, the approach of employing CXCR4‐engineered anti‐EGFRvIII CAR‐NK cells has shown enhanced migration towards glioblastoma sites that produce the specific chemokine CXCL12/SDF‐1." (PMID 40060757, 2025). "In conclusion, CXCL12 conferred immunosuppression mediated by pro-tumorigenic and PD-L1-expressing GAMs in glioblastoma." (PMID 38898023, 2024). "VUF also demonstrated a significant survival benefit in mice with glioblastoma, consistent with the treatment effect observed with CXCL12 inhibitors." (PMID 38898023, 2024). "Recent studies show that targeting CXCL12 can improve the effect of radiotherapy (RT) in preclinical models of glioblastoma (GBM)." (PMID 38806504, 2024). "Hereby, we identified an inverse correlation between CXCR7 and CXCL12 expression in glioblastoma cells." (PMID 38898023, 2024). "Among the various genes affected, SDF1 (CXCL12) was demonstrated to induce AGR2 expression in glioblastoma cells." (PMID 38341509, 2024). "In conclusion, our study revealed that CXCR7 downregulation in glioblastoma cells leads to the accumulation of CXCL12." (PMID 38898023, 2024). "Glioblastoma-derived CXCL12 forms an autocrine-positive feedback loop through the tumor-bound CXCR4 in response to environmental stress." (PMID 38898023, 2024). "Transcriptomic analysis of recurrent glioblastoma specimens indicated an enhanced neuroinflammatory pathway, with CXCL12 emerging as the top-ranked gene in secretory molecules." (PMID 38898023, 2024). "Subsequently, to explore the regulatory role of CXCL12 in GAMs, we analyzed the expression of CXCL12 and IC PD-L1 in a single-cell RNA sequencing (scRNA-seq) dataset obtained from treatment-naïve glioblastoma specimens." (PMID 38898023, 2024). "Single-cell transcriptome profiling of naïve glioblastoma specimens revealed CXCL12 expression in tumor and myeloid clusters." (PMID 38898023, 2024). "Targeted activation of glioblastoma-derived CXCR7 inhibits CXCL12, thereby eliciting anti-tumor immunity and enhancing the efficacy of anti-PD-L1 antibodies." (PMID 38898023, 2024). "The chemokine CXCL12 promotes glioblastoma (GBM) recurrence after radiotherapy (RT) by facilitating vasculogenesis." (PMID 38806504, 2024). "We were unable to detect CXCL12 in supernatants from dissociated glioblastoma tumour biopsy and CUSA samples." (PMID 35464424, 2022). "EGF or HRG have been reported to promote CXCR4 serine and/or tyrosine phosphorylation in glioblastoma or BC cells leading to CXCL12-independent receptor activation of downstream cascades." (PMID 36233192, 2022). "The strategy was also applied in a solid tumor setting, where expression of CXCR4 by EGFRvIII CAR-NK cells induced specific chemotaxis towards the CXCL12/SDF-1α positive glioblastoma cell line U87-MG." (PMID 35242135, 2022). "Retrospective studies showed that the persistant CXCR4/CXCL12 expression after CRT is associated with tumor aggressiveness and poor prognosis in LARC, esophageal cancer, cervical cancer and glioblastoma 32, 53-55." (PMID 34976180, 2022).
glioblastoma (continued). "In glioblastoma multiforme cells, CXCL12/CXCR4 upregulates FOXM1 expression, promoting tumor migration and invasion." (PMID 36591565, 2022). "The CXCR4/CXCR7/CXCL12 signaling pathway plays an important role in proliferation, differentiation, cell survival and chemotaxis in glioblastoma." (PMID 34203660, 2021). "Glioblastoma tumour cells are the main contributors of CXCL12 within the TME, with hypoxic stimuli, TMZ and irradiation further exacerbating production." (PMID 33803414, 2021). "Patients with glioblastoma often deal with resistance to anti-angiogenic therapy due to hypoxia and CXCL12-mediated recruitment of TAMs." (PMID 34503058, 2021). "We observed increased CXCL12 expression in 6/7 glioblastoma tumor cores compared to the peripheral infiltration zone in the same section." (PMID 34162860, 2021). "To test if tumor-associated HSPCs reside in a similar microenvironment, we examined CXCL12 expression in tissue sections from 7 glioblastoma patients, in both the tumor core and the infiltration zone by immunohistochemistry." (PMID 34162860, 2021). "Other secreted factors from SFRP2-overexpressing cells, including CXCL12 have been shown important for the recruitment of immune cells in glioblastoma." (PMID 34021259, 2021). "Utilizing CXCR4 and CXCL12 antibodies markedly inhibited glioblastoma cell proliferation and thus tumor growth." (PMID 34203660, 2021). "The CXCR4/CXCR7/CXCL12 signaling pathway has been extensively studied in recent years and is one of the best-evaluated chemokine signaling pathways in the glioblastoma microenvironment." (PMID 34203660, 2021). "Subsequent analysis showed that CTLA-4 was tightly associated with CXCR3, CXCR6, CXCL12, and T cell immunoreceptor with Ig and ITIM domains (TIGIT) in patients with glioblastoma." (PMID 31911758, 2020). "The CXCR4 receptor promoted specific chemotaxis to glioblastoma cells secreting the CXCL12/SDF-1α chemokine, while the αEGFRvIII-CAR improved the killing specificity and cytotoxicity." (PMID 33391277, 2020). "A recent study showed that the AhR exhibited tumor suppressor-like activity in established and patient-derived glioblastoma cells and genomic analysis showed that this was due, in part, to suppression of CXCL12, CXCR4 and MMP9." (PMID 32731514, 2020). "We previously demonstrated that glioblastoma-initiating cells invade the subventricular zones and promote their radio-resistance in response to the local release of the CXCL12 chemokine." (PMID 30082913, 2019). "Since recurrence of glioblastoma after radiotherapy relies on vasculogenesis, targeting CXCL12/CXCR4 was suggested as a novel therapeutic rationale in combination with radiotherapy in these tumors." (PMID 30813533, 2019). "On the other hand, AurA triggers the CXCL12-mediated migration of glioblastoma cells in vitro as well as the invasion of the subventricular zone in xenograft experiments." (PMID 30082913, 2019). "We used immunofluorescence staining to quantify expression of CXCR4 and CXCL12 in tissue samples from patients diagnosed with glioblastoma, with one cohort comprising samples taken prior to therapy and one with samples taken after therapy." (PMID 30451884, 2018). "In glioblastoma, CXCL12 stimulation of CXCR4 increased cell cycle progression and EMT through expression of survivin." (PMID 29959873, 2018). "It has been reported that both Extracellular Signal-Regulated Kinases 1/2 (ERK 1/2) and Akt are involved in CXCL12-induced proliferation of glioblastoma cells." (PMID 28945785, 2017). "The effects of peptide R on CXCR4 expression, cell survival and migration were assessed on the human glioblastoma cell line U87MG exposed to CXCL12, by immunofluorescence and western blotting, MTT assay, flow cytometry and transwell chamber migration assay." (PMID 27015814, 2016). "The KCa3.1 channels are involved in regulating glioblastoma cell migration in vitro in response to CXCL12 and bradykinin." (PMID 27531900, 2016).
glioblastoma (continued). "The ability of CXCL12 to recruit suppressive myeloid cells was demonstrated in a glioblastoma tumor model." (PMID 25526031, 2014). "By using rat RG2 glioblastoma, we showed that disrupting the CXCL12/CXCR4 axis impairs the characteristics of GSCs." (PMID 23961808, 2013). "Among them, the chemokine CXCL12/SDF-1 appeared of interest as its receptors CXCR4 are widely expressed in glioblastoma tissue, and their activation plays a key role in the migration of glioblastoma cells." (PMID 22675627, 2012). "CPZ1344 activity against the CXCR4/CXCL12 axis was investigated on glioblastoma cells." (PMID 40142155, 2025). "Notably, glioblastoma exhibits elevated levels of the chemokine CXCL12/SDF‐1, primarily expressed in bone marrow stromal cells." (PMID 40060757, 2025). "By integrating the transcriptome data from clinical specimens, in vitro, and in vivo approaches, we unveiled the importance and therapeutic potential of the regulatory mechanisms of CXCR7 on CXCL12 in glioblastoma cells, which consequently affected GAM induction and T-cell alteration." (PMID 38898023, 2024). "Moreover, it was demonstrated that the CXCL12/CXCR4 pathway is overexpressed in histopathological specimens of human glioblastoma." (PMID 36980182, 2023). "In addition, it has been shown that CXCR4 is consistently co-expressed with its ligand CXCL12 in glioblastoma multiforme and that high levels of CXCL12 attract CXCR4-positive vascular and inflammatory cells and promote tumor cytokine secretion." (PMID 37626511, 2023). "In the treatment of CXCL12/SDF-1α-secreting glioblastoma cells, anti-EGFRvIII CAR NK cells were used with overexpression of CXCR4 and the results showed an increase in chemotaxis towards these tumor cells, complete tumor remission in a number of mice, and an increased overall survival." (PMID 34923966, 2021). "MiR-137 suppresses CXCL12 expression, inhibiting glioblastoma progression." (PMID 32280303, 2020). "For example, the attraction between endothelial and glioblastoma cells is maintained by CXCL12 (SDF-1α) binding to the CXCR4 receptor and cytokines, expressed by tumor or stromal cells, best known for their part in mediating leukocyte trafficking and lymphoid tissue development." (PMID 32545571, 2020). "High levels of CXCR4/CXCL12 expression in glioblastomas and in PCNSL have been shown previously." (PMID 32239371, 2020). "Within human glioblastoma tissues, an increased expression of CXCL12 and CXCR4 was localized not only in the regions of tumor necrosis and apoptosis, but also in the areas characterized with high microvessel density, what indicates the importance of this chemokine in the development of these tumors." (PMID 32456359, 2020). "The CXCL12/CXCR4 axis is a key regulator of the post-radiotherapy microenvironment in glioblastoma." (PMID 30813533, 2019). "As a comparison, it has been proved that miR-137 could downregulate KIT or CXCL12 in other cancers such as small cell lung cancer, acute myeloid leukemia, and glioblastoma." (PMID 31032340, 2019). "Altogether, these results show that AurA, a well-known kinase of the mitotic machinery, may play alternative roles in human glioblastoma according to the CXCL12 concentration." (PMID 30082913, 2019). "In fact, it could be shown experimentally that all components of the CXCL12/CXCR4/ACKR3 axis are relevant for recurrence of glioblastoma after radiotherapy, as inhibition of ACKR3 alone in combination with irradiation was also effective in preclinical models." (PMID 30813533, 2019). "There is one study that shows CXCR4‐induced invasion in a 3D setting, increased invasion of glioblastoma spheroids which could be abrogated through proteolytic cleavage of CXCL12 by cathepsin K." (PMID 29959873, 2018). "Moreover, transduction of the YTS NK cell line (containing an EGFR-specific chimeric antigen receptor) with CXCR4 has been shown to enhance infiltration in glioblastoma xenograft models overexpressing CXCL12, resulting in improved survival." (PMID 28923105, 2017).
glioblastoma (continued). "We further evaluated whether CXCL12 is an objective target of miR-137, which would be a potential target for treatment of human glioblastoma." (PMID 29254162, 2017). "Indeed, xenografted glioblastoma cells were recently shown to migrate toward the SVZ upon stimulation by CXCL12, which is secreted by endothelial cells." (PMID 26136659, 2015). "The autocrine/paracrine loop of the CXCL12/CXCR4 pair has been deeply investigated in brain tumors in both in vitro and in vivo models: CXCL12 stimulates proliferation and migration of glioblastoma cells and xenografted tumors inducing ERK1/2 and Akt phosphorylation." (PMID 25484899, 2014). "We then investigated whether the cross-talk between CXCR4 and PDGFR and the effects of AG1296 on CXCL12-induced chemotaxis is a general feature of glioblastoma cells or is a phenomenon confined to GL15 glioblastoma cell line." (PMID 24023874, 2013). "In fact the signaling pathways involved in the pro-migratory action of CXCL12 may differ in individual glioblastoma and integrate with those resulting from abnormal expression and activation of growth factor receptors." (PMID 24023874, 2013). "Several initial mass loadings of CXCL12 tagged with a fluorescent dye (AlexaFluor® 647) were assessed, from 0.4 to 1.6 μg/mL (corresponding to 0.372 to 1.490 μg/mg NPs), which are representative of the concentration range required for therapeutic application targeting glioblastoma cells." (PMID 32295255, 2020). "In a recent study, it has been reported that the overexpression of both CXCR4 and CXCL12 mRNA in glioblastoma cancer stem cells (GBM-CSC) can control proliferation, invasion and angiogenesis." (PMID 30564115, 2018). "In addition, CXCL12 has been reported to be involved into the development of glioblastoma." (PMID 29254162, 2017). "Genetic engineering CAR-NK cells to express the chemokine receptor CXCR4 has resulted in increased migration toward CXCL12/SDF-1α and enhanced in vivo efficacy against CXCL12/SDF-1α-secreting glioblastoma model U-87." (PMID 39134804, 2024). "This highlighted the CXCL12-mediated cell-cell communication, which made our study different to the CXCR7-related intrinsic cellular reaction under irradiation stimuli in glioblastoma." (PMID 38898023, 2024). "MSCs are recruited at the tumor site in response to various chemokines, such as CCL2 or CXCL12, secreted by CD133+ tumor stem cells, as demonstrated in mice bearing glioblastomas." (PMID 39335210, 2024). "In human glioblastoma U87MG, Pt#3 cells, and mouse glioblastoma GL261 cells, CXCR7 agonist VUF11207 (VUF) similarly led to a reduction in CXCL12 expression." (PMID 38898023, 2024). "For example, the expression of the isoforms CXCL12 and IG20/MADD changes during the progression of glioblastoma." (PMID 36675796, 2023). "Specifically, CXCR4 is overexpressed in glioblastoma progenitor cells, and in OSCC, CXCL12 secreted from CAFs recruits monocytes with M2 macrophage behaviors, considerably increasing CSC expansion and inhibiting tumor cell apoptosis." (PMID 37784157, 2023). "Strikingly, VEGF/VEGFR inhibition elevates CXCL12 and CXCR4 expression in the TME of colorectal cancer (CRC) and glioblastoma, thus bypassing VEGF-dependent angiogenesis blockade and contributing to tumor recurrence." (PMID 36568151, 2022). "Following CXCL12 inhibition by NOX-A12, clusters of activated T cells have been observed in the treated CRC and PDAC patients, similar to findings in the glioblastoma patients." (PMID 36568151, 2022). "CD133+ glioblastoma stem cells induce hUCMSC migration to tumor regions by secreting CCL2 and CXCL12." (PMID 33849537, 2021). "When rats bearing glioblastoma multiforme were treated with a combination of anti-VEGF antibodies and NOX-A12, CXCL12 blockade enhanced the effect of anti-VEGF therapy by inhibiting TAM recruitment and further reducing the tumor microvasculature." (PMID 34503058, 2021).